PDCD6-AHRR (PDCD6-AHRR readthrough (NMD candidate))
Gene: Protein-coding gene on chromosome 5 (271,670 to 438,291, forward strand). Ensembl gene ENSG00000288622.
Genetic constraint (gnomAD): Missense variants: 54 observed, 48.16 expected, observed/expected ratio (o/e) 1.12, 90% interval 0.9 to 1.41. Synonymous variants: 24 observed, 18.62 expected, observed/expected ratio (o/e) 1.29, 90% interval 0.93 to 1.77.